PRKRA (protein activator of interferon induced protein kinase EIF2AK2)
Description:
Activates EIF2AK2/PKR in the absence of double-stranded RNA (dsRNA), leading to phosphorylation of EIF2S1/EFI2-alpha and inhibition of translation and induction of apoptosis. Required for siRNA production by DICER1 and for subsequent siRNA-mediated post-transcriptional gene silencing. Does not seem to be required for processing of pre-miRNA to miRNA by DICER1. May function as regulator of gastric epithelial differentiation (By similarity).
Synonyms: PACT; RAX; HSD14; DYT16
Tractability: PROTAC: ubiquitination databases record sites on it; its protein half-life has been measured.
Gene: Protein-coding gene on chromosome 2 (178,431,292 to 178,451,512, reverse strand). Ensembl gene ENSG00000180228.
Subcellular location: Cytoplasm, perinuclear region; Cytoplasm
Subcellular location (Human Protein Atlas): Cytosol; Nucleoplasm
Pathways (Reactome):
Gene expression (Transcription): MicroRNA (miRNA) biogenesis; Small interfering RNA (siRNA) biogenesis
Immune System: PKR-mediated signaling
Gene Ontology:
Molecular function: double-stranded RNA binding; enzyme activator activity; enzyme binding; identical protein binding; pre-miRNA binding; protein binding; protein homodimerization activity; RNA binding; siRNA binding
Biological process: antiviral innate immune response; miRNA processing; pre-miRNA processing; protein stabilization; RISC complex assembly; siRNA processing; immune response; negative regulation of cell population proliferation; regulation of regulatory ncRNA processing; response to virus
Cellular component: cytoplasm; cytosol; membrane; nucleoplasm; RISC-loading complex; nucleus; RISC complex; perinuclear region of cytoplasm
Genetic constraint (gnomAD): Loss-of-function variants: 19 observed, 29.93 expected, observed/expected ratio (o/e) 0.63, 90% interval 0.44 to 0.93. The upper end of that interval is the gene's LOEUF score, 0.93, which puts it in group 3 of 6, group 1 being the genes least tolerant of losing a copy. Missense variants: 317 observed, 369.66 expected, observed/expected ratio (o/e) 0.86, 90% interval 0.78 to 0.94. Synonymous variants: 139 observed, 130.36 expected, observed/expected ratio (o/e) 1.07, 90% interval 0.93 to 1.23.
Homologues: Orthologues: chimpanzee PRKRA (100% identical), dog PRKRA (99% identical), pig PRKRA (99% identical), guinea pig Prkra (99% identical), mouse Prkra (98% identical), rat Prkra (98% identical), rabbit PRKRA (98% identical), tropical clawed frog prkra (58% identical), zebrafish prkra (46% identical), Drosophila melanogaster loqs (34% identical), Drosophila melanogaster Zn72D (9% identical), Caenorhabditis elegans zfr-1 (7% identical), and 2 more. Paralogues in human: TARBP2 (46% identical), ADAR (23% identical), ADARB2 (22% identical), ADARB1 (20% identical), STAU2 (16% identical), ADAD2 (15% identical), STAU1 (13% identical), ADAD1 (12% identical), ZFR2 (11% identical), ZFR (10% identical), ILF3 (10% identical), ADAT1 (9% identical), and 2 more.
Diseases named in the same sentence as PRKRA in open-access papers:
PRKRA is named in the same sentence as 42 diseases in open-access papers, as found by Europe PMC text mining. Sharing a sentence is not in itself a finding about the gene and the disease. The quoted sentences say what the papers report.
Dystonia (23 papers, 2017 to 2025). An abnormally increased muscular tone that causes fixed abnormal postures. "Knockout of Kmt2b in mice forebrain results in altered expression in the dorsal dentate gyrus of a number of genes associated with dystonia including PRKRA and ADCY5." (PMID 39990802, 2025). "In accordance, a P222L mutation in the exon 7 of the PRKRA gene has been previously associated with a young-onset dystonia-parkinsonism disorder." (PMID 39518139, 2024). "Mutations of the PRKRA gene are responsible for the DYT-PRKRA (DYT16) dystonia, characterized by death of neurons in specific brain regions, causing involuntary movements." (PMID 36950523, 2023). "In patient-derived cells carrying the dystonia-causing variant of PRKRA, the affinity of PRKRA-EIF2AK2 interaction is enhanced, and patient fibroblasts exhibit increased and sustained protein kinase R and eIF2α phosphorylation under ER stress." (PMID 37638318, 2023). "Although most PRKRA mutations causing dystonia are recessive, four dominantly inherited variants have also been reported so far." (PMID 36874028, 2023). "We also noted that three of the genes identified as chordoma dependency genes (THAP1, SLC2A1, and PRKRA) are causative for dystonia, a neurological condition characterized by involuntary muscle contractions." (PMID 37024492, 2023). "It has been proven that PRKRA mutation is associated with dystonia, but very few studies have been reported on cancer." (PMID 37484321, 2023). "EIF2AK2 activity is regulated by interferon-induced double-stranded RNA-dependent protein kinase activator A (PRKRA), and a biallelic variant of PRKRA is a confirmed cause of dystonia (DYT-PRKRA) (DYT-PRKRA)." (PMID 37638318, 2023). "Previous studies have confirmed that the mutation in the PRKRA gene is responsible for DYT16, a novel adulthood-onset dystonia, which accounts for 4.5% of all cases." (PMID 37484321, 2023). "The paternal UPiD event on chromosome 2 in P2 uncovered a recurrent missense variant in the PRKRA gene reported in Dystonia 16 (MIM: 612067)." (PMID 36186440, 2022). "Mutations in the stress response gene PRKRA (DYT16), which encodes the protein kinase interferon-inducible double-stranded RNA-dependent activator, were found to cause an autosomal recessive young-onset form of dystonia-parkinsonism disorder in two Brazilian families." (PMID 34360863, 2021). "The highest rates of the variants have been found in the PRKRA and HPCA genes in our dystonia cohort." (PMID 38458754, 2024). "Other genes found to be associated with isolated or combined dystonia include ANO3 (DYT24), TUBB4A (DYT4), GCH1 (DYT5a), TH (DYT5b), TAF1 (DYT3), PRKRA (DYT16), ATP1A3 (DYT12), SGCE (DYT11), KCTD17, and CACNA1A." (PMID 33051750, 2021). "A rare recessively inherited generalized isolated dystonia results from mutation of PRKRA (DYT16) and is characterized by early onset and frequent association with dystonia-Parkinsonism." (PMID 29110692, 2017). "In addition, dysregulation of the integrated stress response has been observed in several monogenic forms of dystonia, including those associated with variants in TOR1A, THAP1, PRKRA, EIF2AK2, and SGCE genes, suggesting a converging pathogenic mechanism." (PMID 40724495, 2025). "Of note, for several established dystonia genes, no carrier of a disease‐causing variant was identified in our large patient group (e.g., in AOPEP, HPCA, PRKRA, and TH)." (PMID 40533913, 2025). "Initial genetic analysis showed that both single-gene and panel (dystonia) sequencing were not conclusive for the following genes: ATP1A3, PRKRA, CACNA1a, DYTPRI, DYT1, and DAT1." (PMID 41153421, 2025).
Parkinsonism (5 papers, 2021 to 2025). Characteristic neurologic anomaly resulting from degeneration of dopamine-generating cells in the substantia nigra, a region of the midbrain, characterized clinically by shaking, rigidity, slowness of movement and difficulty with walking and gait. "In 2008, the ISR branch of cell stress responses per se became implicated in dystonia when the cause for another monogenic form of dystonia and parkinsonism was associated with missense mutations in PRKRA, whose product PACT influences ISR activation." (PMID 38557486, 2024). "Ten different mutations have been identified in PRKRA that cause DYT-PRKRA, which is characterized by progressive limb, laryngeal, and oromandibular dystonia accompanied in some by parkinsonism." (PMID 35625640, 2022). "Mutations in the PRKRA gene cause one form of early-onset, progressive generalized dystonia (DYT-PRKRA) and some of the patients also present with parkinsonism (OMIM: DYT-PRKRA, 612067)." (PMID 35625640, 2022). "From the genetics perspective, parkinsonism is commonly seen in carriers of mutations in DYT genes, such as TAF1 (DYT3), ATP1A3 (DYT12) and PRKRA (DYT16), but especially in those involved in the dopamine synthesis pathway, GCH1 (DYT5a) and TH (DYT5b)." (PMID 34360863, 2021).
dystonia 16 (4 papers, 2022 to 2025). Dystonia 16 (DYT16) is a very rare and newly discovered movement disorder which is characterized by early-onset progressive limb dystonia, laryngeal and oromandibular dystonia, and parkinsonism. "DYT-PRKRA (dystonia 16 or DYT-PRKRA) is caused by mutations in the PRKRA gene that encodes PACT, the protein activator of interferon (IFN)-induced double-stranded (ds) RNA-activated protein kinase (PKR)." (PMID 35625640, 2022). "This is the case for DYT-PRKRA (dystonia 16, DYT16, OMIM#612067), an autosomal recessive disorder caused by pathogenic variants in PRKRA, located on 2q31.2." (PMID 40724495, 2025). "The focus of our research presented here is DYT-PRKRA [also known as dystonia 16 (DYT16)], which is an early-onset, generalized dystonia caused by variants in the PRKRA gene, which encodes the protein PACT, a stress-modulated activator of the protein kinase PKR." (PMID 39512178, 2024).
ovarian carcinoma (3 papers, 2022 to 2024). A malignant neoplasm originating from the surface ovarian epithelium. "PRKRA was also found to promote chemoresistance in ovarian cancer by downregulating miRNA-515-3p and upregulating AXL." (PMID 37484321, 2023). "By binding to Dice, PRKRA downregulated the expression of miRNA-515-3p, leading to the up-regulation of target gene AXL and oxaliplatin resistance of ovarian cancer." (PMID 37484321, 2023). "PRKRA is an activator of PRKR kinase, and its knockout may result in enhanced sensitivity for chemotherapy (oxaliplatin) mouse ovarian cancer cells." (PMID 35409691, 2022).
viral infection (3 papers, 2012 to 2023). "PRKRA participates in inflammation and the response to environmental stress, especially in viral infection." (PMID 37484321, 2023).
asthma (2 papers, 2022 to 2025). "The final two asthma-associated CNVs are partial gene duplications on chromosome 2 (affecting exons 4–8 of the PRKRA gene and the 3’ end of the CHROMR long non-coding RNA gene) and chromosome 12 (affecting exon 2 of the FBRSL1 gene)." (PMID 35597955, 2022). "The associations of PRKRA and FBRSL1 CNVs with asthma were also abolished by conditioning on certain HLA variants." (PMID 35597955, 2022). "The association with asthma is therefore not necessarily with the PRKRA gene but potentially with HLA variation in linkage disequilibrium (LD) with the presence/absence of the pseudogene." (PMID 35597955, 2022).
mucinous ovarian cancer (2 papers, 2021 to 2023). An invasive malignant neoplasm that arises from the ovary and is characterized by the presence of malignant epithelial cells that contain intracytoplasmic mucin and may resemble the epithelial cells of the endocervix or gastrointestinal tract. "PRKRA has been implicated in conferring chemoresistance to mucinous ovarian cancer cells and in antiviral response." (PMID 36950523, 2023). "Consistently with the frequent occurrence of the mutation in OV, the changes in the PRKRA level were recently linked with the resistance of mucinous ovarian cancer to the miR-515-3p dependent platinum-based (oxaliplatin) treatment." (PMID 33406242, 2021). "It is still to be determined if PRKRA acts in a similar fashion in glioma as it does the mucinous ovarian cancer cells, as gliomas are notoriously resistant to chemotherapeutic agents." (PMID 36950523, 2023).
pancreatic cancer (2 papers, 2023 to 2024). "Lu et al29 found that S100PBP may inhibit pancreatic cancer cell adhesion through the LMNB1 and PRKRA gene pathways." (PMID 39128058, 2024).
adenoma (1 paper, 2013). A neoplasm arising from the epithelium. "Here, we evaluated the mRNA expression of DROSHA, DGCR8, DICER (DICER1), TARBP2, and PRKRA, the core components in the miRNA biogenesis pathway, in a cohort of 73 adrenocortical tumors (including 43 adenomas and 30 carcinomas) and nine normal adrenal cortices using a RT-qPCR approach." (PMID 23671264, 2013).
adrenocortical tumors (1 paper, 2013). "We analyzed the mRNA expression levels of five miRNA-processing genes (DROSHA, DGCR8, DICER, TARBP2, and PRKRA) in 73 adrenocortical tumors and nine adrenal cortices using RT-qPCR." (PMID 23671264, 2013).
AIDS (1 paper, 2011). A syndrome resulting from the acquired deficiency of cellular immunity caused by the human immunodeficiency virus (HIV). "While neuroinflammation is a cardinal feature of HAD, antiviral responses including induction of IFN-α, MX-1, PRKRA or BST-2 await clarification of their expression in HAD, although several studies indicate the IFN-α might be increased in the brains of HIV/AIDS patients." (PMID 21645334, 2011).
atopic dermatitis (1 paper, 2015). "We further identified previously unreported pleiotropic alleles with opposing effects on atopic dermatitis and psoriasis risk in PRKRA and ANXA6/TNIP1." (PMID 25574825, 2015).
atrial fibrillation (1 paper, 2025). A disorder characterized by an electrocardiographic finding of a supraventricular arrhythmia characterized by the replacement of consistent P waves by rapid oscillations or fibrillatory waves that vary in size, shape and timing and are accompanied by an irregular ventricular response. "PRKRA has been implicated in studies impacting heart structure, and while FKBP7 has been less discussed, was linked to atrial fibrillation in one study." (PMID 39670392, 2025).
brain glioma (1 paper, 2023). A malignant glioma that involves the brain. "This confirms that a lower mRNA PRKRA/lncRNA CHROMR ratio (and thus a high expression of lncRNA CHROMR) is a feature of brain glioma." (PMID 36950523, 2023). "This reduced the mRNA PRKRA/lncRNA CHROMR ratio in LGG and GBM samples by a log2-fold change of 2.81 and 2.57, respectively as compared to normal brain tissue, which suggests a high expression of lncRNA CHROMR is characteristic of brain gliomas." (PMID 36950523, 2023).
breast carcinoma (1 paper, 2023). "In addition, PRKRA promoted breast cancer metastasis through SUMOylation of Rac1." (PMID 37484321, 2023).
chordoma (1 paper, 2023). Chordomas are rare malignant tumors arising from embryonic remnants of the notochord in axial skeleton. "Genes were selected to represent both those functionally connected to other chordoma dependency genes (PTPN11, FANCM, ADAR, PRKRA, SOX9, SRRM2, SLC2A1, and SLC7A5), as well as those with putatively unique effects (LUC7L2 and CDK6)." (PMID 37024492, 2023).
chronic hepatitis C (1 paper, 2019). "We sought to determine if the baseline hepatic levels of miR-122, miR-29b, Claudin, Occludin, Protein Kinase R (PKR) or PKR activator (PRKRA) were correlated with HCV RNA or stage of fibrosis in patients with chronic hepatitis C (CHC)." (PMID 30957098, 2019).
colon cancer (1 paper, 2016). "PRKRA rs10207436 was associated with reduced colon cancer risk (under the dominant model), while MAPKAPK2 rs4548444 was associated with increased risk (under the recessive model)." (PMID 27107574, 2016). "Eleven SNPs were associated (P < 0.05) with colon cancer risk, and two of these variants remained significant after correction for multiple comparisons (PHolm < 0.05): rs1967327 (PRKRA) (ORdom = 0.78, 95 % CI 0.66–0.92) and rs4548444 (MAPKAP2) (ORrec = 1.67, 95 % CI 1.12–2.48)." (PMID 27107574, 2016).
colorectal cancer (1 paper, 2023). A primary or metastatic malignant neoplasm that affects the colon or rectum. "Increased expression of PRKRA can be associated with worse survival of colorectal cancer patients." (PMID 37869102, 2023).
COVID-19 (1 paper, 2020). A disease caused by infection with severe acute respiratory syndrome coronavirus 2. "We also identified two additional genes, PRKRA and LAPTM4B, for which the probability of observing a deleterious variant was computed higher in the COVID-19 samples compared to controls." (PMID 33206719, 2020).
dilated cardiomyopathy (1 paper, 2025). Cardiomyopathy which is characterized by dilation and contractile dysfunction of the left and right ventricles. "It is worth noting that FKBP7, PRKRA, and third gene (PLEKHA3, significant with LVM, LVEDV, and LVESV), all lie within a region of chromosome 2 that also includes the gene TTN, which is well established heritable cause of dilated cardiomyopathy, a leading cause of heart failure." (PMID 39670392, 2025).
glioblastoma (1 paper, 2023). The most malignant astrocytic tumor (WHO grade IV). "Here we report a link between glioma patient survival and the lncRNA CHROMR gene, which could be linked with the overlapped PRKRA gene in glioblastomas." (PMID 36950523, 2023). "The fact that PRKRA/CHROMR ratio, but not the genes separately, had an effect on survival of glioblastoma patients, suggests that CHROMR may indeed have some NAT-associated interaction with the overlapped PRKRA gene in glioblastoma, but not low-grade glioma." (PMID 36950523, 2023).
liver cancer (1 paper, 2023). An epithelial or non-epithelial malignant neoplasm that arises from the liver. "For example, lncRNA AL033381.2 could bind to PRKRA and up-regulate the expression of PRKRA, thereby promoting the progression of liver cancer." (PMID 37484321, 2023).
lung carcinoma (1 paper, 2021). "PRKRA showed the most significant expression-driven dependency (R = −0.46, FDR = 1E − 3) in lung cancer cell lines and was overexpressed in 7% of LUAD cases, whereas its phosphosite PRKRA p.S130 is over-phosphorylated in 15% of LUAD." (PMID 34552204, 2021).
pancreatic ductal adenocarcinoma (1 paper, 2023). An infiltrating adenocarcinoma that arises from the epithelial cells of the pancreas. "The results of IHC showed that PRKRA was upregulated in pancreatic ductal adenocarcinoma cells than paired normal pancreatic ductal cells in specimens from patients." (PMID 37484321, 2023).
psoriasis (1 paper, 2015). An autoimmune condition characterized by red, well-delineated plaques with silvery scales that are usually on the extensor surfaces and scalp. "The lead variant within PRKRA might mediate opposing effects in AD and psoriasis via miRNA processing and/or cellular response to environmental stress, and we hypothesize that this reflects the striking differential susceptibility to viral and bacterial skin infections observed in AD and psoriasis." (PMID 25574825, 2015). "Two of the loci displaying opposing effects (ANXA6/TNIP1 and PRKRA) have not previously been reported in association with psoriasis and/or AD." (PMID 25574825, 2015).